IL10 (interleukin 10)
Diseases named in the same sentence as IL10 in open-access papers (continued):
Sharing a sentence is not in itself a finding about the gene and the disease.
infection (continued). "Up regulation of IL-10 in co-infections is probably indicative that co-infected individuals don’t lose the protective role of the IL-10 against soil borne helminths during infection." (PMID 29560020, 2018). "To test the role of TNF in neuroimmunopathology and astrocyte activation in this infection, we treated IL-10 KO mice with neutralizing anti-TNF antibody or isotype control antibody for 5 days (days 5–9 p.i.)." (PMID 29866139, 2018). "Strikingly, blockade of IFNAR signaling after the first week of infection resulted in approximately a 60% increase in the proportion of IL-10-producing Tfh cells which was further associated with a 25% increase in the proportion of GC B cells on day 21 p.i.." (PMID 30487586, 2018). "Omega-9 decreased the production of proinflammatory cytokines, increased IL-10 production, reduced neutrophil migration and accumulation in the site of infection, and also improved bacterial clearance." (PMID 30538802, 2018). "Studies on experimental and natural human infections with hookworms have observed that the infection triggers strong Th2 cytokines (especially IL-4, IL-5, IL-9 and IL-13), regulatory IL-10 and TGF-β1 responses." (PMID 30274434, 2018). "The results demonstrated that lung homogenates obtained from mice following 60 days of infection (black bars) have increased levels of pSTAT3 and IL-10 proteins when compared to similar samples obtained from naïve mice." (PMID 30413750, 2018). "The Th1 responses and regulation of the recruitment of Th1 immune cells to the site of infection are characterized by expression of key cytokines and chemokine such as TNFα, IL-12, IFNγ, IL-6, IL-10 and MCP-1 among others." (PMID 30413750, 2018). "Deficiency of IL-27 signaling results in significant reduction of IL-10-producing T cells during autoimmune disease and infection." (PMID 29535721, 2018). "Strikingly, LMWH treatment of IL-10 KO mice rescued them from fatal neurologic disease before day 9 post-infection." (PMID 29866139, 2018). "In summary, MHV-68 infection in IFNγR−/− mice causes severe GI dilatation with attendant macrophage invasion and SMC degradation that is closely associated with reduced IL-10 expression." (PMID 30249047, 2018). "In contrast, inbred C57BL/6 mice displayed increased pro-inflammatory cytokines coupled with IL-10, on day 10 post-challenge, after which the majority of inbred mice succumb to infection." (PMID 30533047, 2018). "In the case of IL-10, its gene expression was very low and it was unaffected by the infection or the dietary supplementations." (PMID 29942312, 2018). "We also found that WT mice presented increased number of CD4+ IL-10+ T cells in LNs when compared with ST2−/− mice at the 7th day post-infection." (PMID 29867945, 2018). "Single infections with E. tenella evoked host immune response which led to significant expression of cytokines such as IL-10 and IFN-γ in the ceca." (PMID 30081942, 2018). "Since blocking of CD200–CD200R signaling following LdWT infection correlated with the suppression of IL-10 producing CD4+ T cells, we were particularly interested to further characterize these cells." (PMID 29915577, 2018). "Surprisingly, production of IL-10 in the lungs of A54970 infected mice was notably two-fold higher than A28006 infection." (PMID 30518854, 2018). "This matches the increase of serum antibody levels observed post-infection and the significant positive relations between IL-4, IL-10 and antibody titers shown in this study, indicating a Th2-biased immune response." (PMID 29973271, 2018). "Three traits were measured: weight gain (WG) during the period of infection, caecal lesion score (CLS) post mortem, and the level of a serum biomarker of intestinal inflammation, i.e. circulating interleukin 10 (IL-10), measured at the height of the infection." (PMID 30463512, 2018).
infection (continued). "Accordingly, previous infection of IL-10−/− mice with a S. Typhimurium ΔTTSS-1, that has a functional TTSS-2, is still able to promote inflammation in the intestine." (PMID 29896196, 2018). "Inflammatory cell numbers were also significantly reduced by IL-10 treatment at 7 and 10 days post-infection (p = 0.028 day 7, p = 0.036 day 10)." (PMID 30249047, 2018). "Comparative analysis of the expression of cyclin genes in IL10–1 and CC3 showed that F-box domain Skp2-like genes were suppressed in IL10–1 during the infection of M. incognita, particularly at 1 dpi compared with those in CC3." (PMID 30075750, 2018). "For IL-10−/− mice, we used a dose and an infection time that was higher than the dose and time chosen for WT mice, because the former mice are more resistant to S. Typhimurium infection." (PMID 29896196, 2018). "In non-humanized mouse models of S. aureus infection, the induction of IL-10 appears to play opposing roles depending on the site of infection." (PMID 29843476, 2018). "Infection of human monocyte-derived macrophages similarly demonstrated M5 protein-dependent secretion of IL-10, indicating that the M5 protein promotes IL-10 secretion from infected macrophages of both human and mouse origin." (PMID 29579113, 2018). "The initial IL-10-mediated anti-inflammatory response was rapidly overwhelmed at the later stage of infection." (PMID 29774023, 2018). "Small intestinal Treg of GF mice were rather poor IL-10 producers at steady state and upon infection." (PMID 30349532, 2018). "Following injury/infection resolution, secretion of factors including interleukin-10 (IL-10) and transforming growth factor beta (TGFβ) by fibroblasts and platelets promote the polarization of anti-inflammatory macrophages." (PMID 29867776, 2018). "Since an interaction loop of gp91phox-ROS-NF-κB p65 was detected in the senescent macrophages during PAO1 infection, we assessed the production of ROS and the expression of inflammatory cytokines including IL-6, IL-10, and TNFα." (PMID 30050663, 2018). "While the secretion of proinflammatory cytokines IL-6 and TNFα was similar in both infections, the output of regulatory IL-10 was significantly higher in wild type infection, indicating that the M5 protein promotes secretion of IL-10." (PMID 29579113, 2018). "In summary, the ameba needs to balance IL-10 and the pro-inflammatory cytokine to allow establishment of infection." (PMID 30406037, 2018). "Kinetic analyses of cytokine secretion from infected B6 macrophages further established a key role for the M5 protein in driving secretion of IL-10, which reached peak levels at 12 hours post infection." (PMID 29579113, 2018). "We were also interested to see if CD4 T cells, the primary producers of IL-10 in this infection, were also found localized with fibrin(ogen) in the vessels." (PMID 29866139, 2018). "The cytokine production levels of TNF-α, IL-1β, and IL-10 in the cell-free culture supernatants were significantly enhanced in response to S. aureus at 24 h after infection." (PMID 29523806, 2018). "Some pathogens can harness the immunosuppressive capacity of IL-10 to limit host immune responses, leading to persistent infection [as reviewed in Ref." (PMID 29686676, 2018). "IL-10 is produced after E. maxima and E. tenella primary infection of White Leghorn chickens (lines 15I and C.B12) and E. tenella primary infection of commercial broilers." (PMID 30534137, 2018). "The expression of IL-6 and TNF-α at initial stages of infection and IL-10 at longer stages was also detected in the serum of mice infected with S. aureus; however, in all these reports, a molecular mechanism was not described." (PMID 29434603, 2018). "The impairment of IL-10 expression or signaling can result in enhanced removal of pathogens during an acute infection but also can contribute to an exacerbated inflammatory response, resulting in immunopathology and tissue damage." (PMID 30186038, 2018).
infection (continued). "IL-10 has potent anti-inflammatory properties and contributes to limiting the immune response to infection, thereby preventing damage to the host and maintaining normal tissue homeostasis." (PMID 29715306, 2018). "Our IL-10+IL-21+ CD4-depletion experiments indicate that early inflammatory signals propagated during the first few weeks of LCMV Cl13 infection are necessary for the formation of IL-10+IL-21+Tfh cells." (PMID 30487586, 2018). "RNA-based next generation sequencing revealed an up-regulation of Il10, Il10rα and further genes involved in IL-10 downstream signaling, including Jak1, Socs3 and Stat3 in the brain upon infection." (PMID 29666403, 2018). "This high IL-10 production in the beginning of infection in WT mice possibly favored bacterial growth." (PMID 29867945, 2018). "IL-10 is upregulated during acute v2.2-1 infection, at which time it is mainly produced by CD4+ and to a lesser extent CD8+ T cells." (PMID 30619363, 2018). "The concentrations of MCP-1 (CCL2), IL-10, and IL-12p70 in the serum from both B6 C5+/+ and B6 C5+/+ mice were below detectable levels on the third and the sixth days post-infection." (PMID 29568732, 2018). "This study therefore determined the levels of cytokines (IL-10, IFN-γ and TNF-α) that are linked with the ability of MTB to evade the host’s immune system and mediate long-term infections in the lungs, leading to chronic tuberculosis." (PMID 30583589, 2018). "Bronchial epithelial cells carrying rs35699176 responded with a stronger inflammatory IL-6 and IL-10 response to A. fumigatus conidia after infection." (PMID 30237437, 2018). "Trait weightings of the first eigenvector, (EV1, eigenvalue = 59%), were biologically interpreted as representing a response of birds that were susceptible to infection, with low WG, high CLS and high IL-10." (PMID 30463512, 2018). "In our study, IL-10 levels decreased in IFNγR−/− mice with GI tract dilatation after infection, potentially leading to decompensation and exacerbating inflammatory reactions." (PMID 30249047, 2018). "Conversely, the presence of platelets in the context of infection decreased the secretion of the anti-inflammatory cytokine IL-10." (PMID 29867977, 2018). "First, we quantified the expression of il10, tnfa, tnfb, and il1b in the abdominal organ blocks of zebrafish at early time points during an infection." (PMID 29985419, 2018). "Our initial findings were also validated in vMC0-infected BN rats, where infection resulted in the induction of genes associated with macrophage M2 activation (MGL1, ARG1, IL10, and IL10RA) and Th2 genes (IL33 and IL25)." (PMID 30150981, 2018). "In humans with HGA, mild clinical manifestations and recovery from infection is temporally associated with a dominant IFN-γ immune response and moderate levels of IL-10." (PMID 30563470, 2018). "Right: graph of the lowest abbreviated SHIRPA score in individual mice before day 9 post-infection with infected IL-10 KO mice grouped according to outcome." (PMID 29866139, 2018). "Taken together, macrophages infected with O. tsutsugamushi are the primary source of IL-10, which suppresses the generation of antigen-specific T cells, especially Th1 and CTLs, during the acute phase of infection." (PMID 30233599, 2018). "IL-10 expression at the time of FIV infection was greater in the PLV when compared to SHAM cats, and the predicted suppression of proviral loads two weeks FIV PI in the CO cats." (PMID 29677149, 2018). "Compared with control mice, the PAS-5-immunized mice exhibited increased levels of serum antibodies and cytokines (except for IL-10) at different time points post-infection." (PMID 29843794, 2018). "While miR-150 targets IL-10 and IL-18 in leukocytes, microRNA-342 contributes to broad host cell immunity against infection." (PMID 30332984, 2018). "Increasing IL-10 levels in conjunction with decreasing mHLA-DR is also a feature of the inflammatory response following severe infection." (PMID 30212506, 2018).
infection (continued). "IL-10 levels were increased during infection; these levels were significantly higher in infected untreated mice than in non-infected mice, and Ext-Ts reduced the cytokine levels relative to PbA-infected mice, although not statistically significantly." (PMID 29367729, 2018). "Regarding IL-10, infection of C57BL/6 mice with PbA leads to increased levels of IL-10 in serum samples and IL-10 transcripts in cerebral tissues." (PMID 29367729, 2018). "As one of the immunosuppressive cytokines secreted by Tregs, the roles of IL-10 in infection are unclear." (PMID 30116243, 2018). "We also established that Treg cells increased their capacity to produce regulatory cytokines, such as TGF-β (as indicated by co-expression of GARP and LAP) and IL-10 after 20 days of infection." (PMID 30455700, 2018). "Surprisingly, MPI cells challenged with live Mtb also produced detectable amounts of IL-10 at 24 h post-infection (120 and 230 pg/mL at MOI 10 and 20, respectively)." (PMID 29593716, 2018). "Levels of TNF-α, IL-10 and IL-2 differed between groups on SD 1 already, i.e. before infection, but these discrepancies are compensated for by the paired analysis (normalization to SD 1) applied here." (PMID 29973271, 2018). "Expression of the regulatory cytokine IL-10 was up-regulated very early during infection in this host species while TGF-β4 mRNA expression levels were unchanged during the experiment." (PMID 30450097, 2018). "In experimentally infected calves, a systemic regulatory response develops during the chronic stages of infection, characterized by increased parasite-specific IL-10 and TGF-β production by PBMCs." (PMID 28993458, 2018). "Nonetheless, in white blood cells, IL-4, IL-6 and IL-10 mRNA-levels significantly increased after infection, whereas IFN-ɣ, IL-2 and TGF-β expression tended to decrease." (PMID 29973271, 2018). "In conclusion, the present study reveals neuroprotective properties of intact IL-10R signaling and highlights the importance of the IL-10 pathway in maintaining hippocampal integrity in SJL mice following TMEV infection." (PMID 29666403, 2018). "We detected significantly higher amounts of IL-10 in the supernatants of MoDCs challenged with STM-D23580 as compared to STM-LT2 at later stage of the infection." (PMID 30451854, 2018). "The suppressive role of type I IFN/IL-10 during the generation of adaptive T cell immunity has been well-established in various infections." (PMID 30233599, 2018). "As expected, the A54970 infection of BMDMs from IL-10−/− mice was unable to inhibit E. coli response; furthermore, their phagocytic and microbicidal abilities were not altered in IL-10−/− cells." (PMID 30518854, 2018). "WT mice were sacrificed at the peak of infection (day 10 p.i.)and IL-10 KO mice upon severe morbidity as determined via SHIRPA score." (PMID 29866139, 2018). "The most critical factors highlighted during the analysis of the Treatment response model include IL-10, IL-21, IL-12, IL-2 which determine the treatment outcome in terms of clearance of infection by modulating pro-inflammatory response." (PMID 29891859, 2018). "The titers of IL-10 were detectable early in infection (10 pg/mL at 1 and 2 dpi) compared to uninfected controls and peaked at 16.44 pg/mL by 3 dpi, with low expression levels maintained throughout the infection." (PMID 29511145, 2018). "In the present study, we observed lower concentrations of Th1 cytokines (IFN-γ, TNF-α, IL-6) on day 3 post-infection) and lower concentrations of one Th2 cytokine (IL-10) in infections of BCG+ donor PBMCs compared to BCG- donor PBMCs." (PMID 30204787, 2018). "In contrast, the infection alone showed an inadequate drop in IFNγ, IL-2, and IL-10 levels over the course of infection." (PMID 29740435, 2018). "Analyzing the inflammatory response in the lungs, we saw, as expected, an induction of pro- (IL-1β, TNF-α, KC, IL-6) and anti-inflammatory (IL-10) chemo- and cytokines following infection with S. pneumoniae." (PMID 29449834, 2018).
infection (continued). "We have now identified a smaller set of behavioral symptoms, described in the “Methods” section, that specifically change at the time that IL-10 KO mice begin to succumb to infection." (PMID 29866139, 2018). "In the present study, spleen cells displayed an increase of IL-10 mRNA at the early stage of infection, but with a delayed increase of Foxp3 mRNA at the middle stage and a decrease of IFN-γ mRNA at the late infection stage." (PMID 30037796, 2018). "In contrast, anti-inflammatory cytokines, mainly IL-10, lead to proliferation of parasites and interfere with infection control." (PMID 30175073, 2018). "We verified that IL-10 was able to inhibit inflammasome activation by A28006 infection, resulting in low levels of IL-1β as well as LDH production." (PMID 30518854, 2018). "Another molecule counteracting tissue damage is the anti-inflammatory cytokine IL-10, known to be a master regulator of immunity to infection as well as balancing immune responses and neurodegeneration in the brain." (PMID 30619363, 2018). "In the BALB/c model, numerous evidences suggest that the control of the infection not only depends on the induction of IFN-γ-mediated responses, but also on the control of IL-10 and IL-4 cytokines that are associated with pathology." (PMID 28558043, 2017). "The A allele in TNFα-308G/A SNP was found more frequently in individuals with asymptomatic infection (16% vs 7%), whereas the CC genotype in IL-10-819 C/T SNP was more frequent in patients with CCL (34% vs. 27% in asymptomatic individuals)." (PMID 28241747, 2017). "The effects of pleiotropic IL-10 during the course of infection are nonetheless multiple and the subtle IL-10-governed mechanisms that balance inflammation and immunoregulation are still subject to plenty of attention." (PMID 28316998, 2017). "HK-Pg infection of BMM induced similar levels of TNFα, IL-12p70, IL-6, IL-10, and IFNβ compared to infection with viable P. gingivalis." (PMID 28824884, 2017). "The IL-4, IL-6, IL-10, IL-13 levels of Th2 cells continued to increase after infection during the first 9 weeks post-infection and down-regulated thereafter." (PMID 29192177, 2017). "IgM levels correlated with low levels of some pro-inflammatory markers and higher IL-10 levels, probably still reflecting an immunosuppression of the acute phase of the infection." (PMID 28628613, 2017). "In infection with the Flavivirus Japanese Encephalitis virus, IL-10-producing CD4+ Foxp3+ natural Treg cells improve survival in a murine model probably by controlling the immunopathology." (PMID 28316998, 2017). "It was previously shown that infection with Col1.7G2 induces high expression of IL-10 by human monocytes, as compared to Y strain, and that this increase was not dependent on parasite contact, since it was observed in CFSE+ and CFSE- cells." (PMID 29176759, 2017). "Increased susceptibility or resistance to infection with C. albicans were both showed in TLR2-deficient mice, due to reduced proinflammatory cytokines production or decreased IL-10/increased IL-12 and IFN-γ production, respectively." (PMID 29238325, 2017). "IL-10+ DCs increase in frequency during the acute phase of Cl13 infection and then decline with time." (PMID 28316998, 2017). "Increase in levels of IL-10, an anti-inflammatory cytokine and reduction of neutrophils in lungs facilitated the control of infection." (PMID 28963492, 2017). "Expression of the IL-10 gene was also increased in caspase-6-/- mice as early as 6 hours after infection." (PMID 28686630, 2017). "There is convincing evidence that following infection with Leishmania major and Schistosoma mansoni IL-10-producing B cells (B10 cells) have strong immunosuppressive activity." (PMID 28732522, 2017). "On the other hand, serum level of IL-10 kept rising and maintained a plateau from 5 to 12 wks post infection." (PMID 28614408, 2017).